EZH2 (enhancer of zeste 2 polycomb repressive complex 2 subunit)
Diseases named in the same sentence as EZH2 in open-access papers (continued):
Sharing a sentence is not in itself a finding about the gene and the disease.
cancer (continued). "Interestingly, EZH2 has been reported to enhance tumorigenicity by blocking differentiation of cancer cells in solid as well as hematopoietic tumors." (PMID 27158195, 2015). "If certain independent clinicopathological features for cancer survival were identified, the combination of EZH2 status and these clinicopathological factors might provide more accurate assessments of cancer prognosis." (PMID 25974088, 2015). "Collectively, considering of the enrichment of tumorigenic cancer cells at xenotransplanation, our findings agree that pharmacological interference with EZH2 might be a promising therapeutic approach to targeting HCC." (PMID 26062443, 2015). "Our results may provide an explanation for the phenomenon that inhibitors of DNMT or EZH2 reverse repressive epigenomes to resensitize radioresistant cancer cells to ionizing radiation." (PMID 25460508, 2015). "Despite its increased activity on H3K27me1 (with little gain in activity for H3K27me2), the observation that EZH2 A687V can drive conversion of H3K27me2 to H3K27me3 is in line with previous reports that have both predicted and demonstrated this ability in cancer cell lines." (PMID 25671303, 2015). "In other solid tumors, the levels of miR-101 were also decreased in neoplastic tissues, and miR-101 could inhibit the tumorigenesis and/or cancer progression by repressing the oncogenes EZH2 and COX2." (PMID 25693145, 2015). "Enhancer of zeste homolog 2 (EZH2) and HDACs were recently identified as critical histone modifiers of deregulated miRNAs in cancer and can be recruited to a miRNA promoter by transcription factors such as v-myc avian myelocytomatosis viral oncogene homolog (MYC)." (PMID 26703582, 2015). "There is excitement over the potential of EZH2 inhibitors to treat cancer, and their ability to augment protective cytokine pathways (e.g. IFNγ) could boost efficacy." (PMID 26030458, 2015). "In addition, the MYC oncogene can also stimulate EZH2 expression and has been suggested to interact with the Polycomb machinery at multiple levels in cancer." (PMID 26637281, 2015). "Furthermore, small molecule inhibitors of EZH2 catalytic activity have been developed and tested in a variety of cancers." (PMID 25924914, 2015). "For example, EZH2 recruits DNA methyltransferases to Polycomb-silenced genes inducing de novo DNA methylation patterns, a fact which is especially important in stable gene silencing of cancer cells." (PMID 26029238, 2015). "Moreover, inhibition of the HMT EZH2 or G9a promotes autophagy in cancer cells while the use of HDACi gave contradictory results on autophagy levels in cancer cells." (PMID 26474850, 2015). "Numerous reports have suggested that EZH2 expression might play meaningful prognostic roles in certain cancers." (PMID 25974088, 2015). "PRC2 could regulate both stages, thus EZH2 inhibitors should be assessed in cancer prevention as well as therapy of advanced tumors." (PMID 26030458, 2015). "Using miRNA target prediction algorithms, we identified many cancer-related genes, among which, EZH2 may be a potential direct target of miR-506." (PMID 26452129, 2015). "Next, we investigated in vitro whether miR-101 could regulate EZH2 expression in eRMS cells, as reported for other types of human cancers." (PMID 26251675, 2015). "Therefore, further characterization of cooperative activities of H1.2 and EZH2 has potential implications in terms of cancer treatment." (PMID 26581166, 2015). "Our results suggested that EZH2 might be an independent prognostic factor for multiple survival measures in different cancers." (PMID 25974088, 2015). "However, in several cancer types, only a few clinicopathological features were correlated with EZH2." (PMID 25974088, 2015). "Cytokines have pleiotropic effects on tumorigenesis, and could have a major influence on the efficacy of EZH2 inhibitors in human cancer." (PMID 26030458, 2015).
cancer (continued). "EZH2 is one of several chromatin regulatory proteins that have prompted great clinical and scientific interest as they offer the possibility of new therapeutic targets in cancer." (PMID 26268310, 2015). "Together, these results demonstrate E2 may promote cancer progression through the ERs/EZH2/DAB2IP pathway." (PMID 26587829, 2015). "Therefore, we conducted a systematic review and quantitative meta-analysis to clarify the prognostic value of EZH2 expression in human cancers." (PMID 25974088, 2015). "EZH2 is often over-expressed in several human cancers acting as an oncogene." (PMID 26251675, 2015). "Dysregulation of EZH2 alters the expression of many cancer related genes." (PMID 25944687, 2015). "Therefore, the PI3K/AKT pathway is of importance in both EZH2 regulation and biological function in cancer development and further in depth study is necessary." (PMID 26265454, 2015). "However, a dual methylation and silencing mechanism exists in cancer, in which EZH2 is also able to recruit DNA methyltransferases (DNMTs) to direct DNA methylation." (PMID 26304929, 2015). "This makes the inhibition of EZH2 an important target in the development of cancer therapeutics." (PMID 24587223, 2014). "Notably, PRC2 target genes tend to be DNA hypomethylated in cancer cells that show high levels of Polycomb components such as Ezh2." (PMID 25333635, 2014). "Results from preclinical studies forecast great promise for inhibitors of EZH2 catalysis as treatment for such genetically defined cancers, and EZH2 inhibitors may also mitigate chemotherapy resistance." (PMID 25493630, 2014). "The abnormal expression of EZH2 is involved in the tumorigenic types of cancer with poor prognoses." (PMID 25036033, 2014). "As an additional promising approach, we investigated whether pharmacological inhibition of EZH2 in RD cells by either reducing its expression or catalytically inhibiting its activity might be detrimental for cancer cell proliferation both in vitro and in vivo." (PMID 24575771, 2014). "Whether EZH2 over-expression had any effect on NSC745885 cytotoxicity of other cancer cells was further investigated." (PMID 25431950, 2014). "Moreover, EZH2 over-expression of cancer cells attenuates the NSC745885-mediated growth inhibition, indicating that EZH2 is a major target responsible for NSC745885 pharmacologic anti-cancer activity." (PMID 25431950, 2014). "This high expression of EZH2 is related to poor prognostic in these cancers and tumors." (PMID 24852755, 2014). "Notably, siITGα2 mainly on HCTshEZ-2 and DLD1 cells increased migration capacity by roughly 25% and 12% respectively, confirming that the EZH2-silenced ITGα2-cofilin axis is important for cancer cell locomotion." (PMID 25549357, 2014). "The depletion of EZH2 and H3K27me3 triggers the apoptosis of cancer cells." (PMID 25255316, 2014). "This could be a consequence of genetic alterations in enzymes regulating epigenetic patterns, such as gene mutations found in human myeloid malignancies, including DNMT3a, TET2, IDH1, IDH2, EZH2, or ASXL1." (PMID 24944583, 2014). "Given EZH2’s multi-faceted function and role in cancer, context-specific strategy for targeting EZH2/EZH2-mediated signaling could serve as future targeted therapy/personalized medicine for human cancer." (PMID 25520914, 2014). "Therefore, normalizing H3K27me3 by targeting inhibition of EZH2 seems to become a potential new method for cancer therapy." (PMID 25535400, 2014). "EZH2, deregulated in a wide range of cancers, exerts its functions in distinct action modes." (PMID 25520914, 2014). "A role for Ezh2 in repressing Mmp9 could have implications in the development of therapeutic strategies for cancer." (PMID 25359725, 2014). "EZH2 is overexpressed in aggressive forms of prostate, breast and bladder cancer." (PMID 25295088, 2014). "Targeting EZH2 with drugs like GSK126 may not only induce apoptosis by itself but also sensitize cancer cells to other agents of chemotherapy." (PMID 25341040, 2014).
cancer (continued). "In the mean time, EZH2 expression was increased in the cancer specimens." (PMID 25341040, 2014). "There were also gene sets related to cancer signaling pathways (MYC, STAT3, and CDH1) or genes moderately involved in cancer (IRF4, SOX4, and EZH2), as well as some associated with various aspects of cancer such as cell transformation, metastasis, and response to therapeutics." (PMID 25122487, 2014). "EZH2, a critical component of the PRC2, has intrinsic histone methyltransferase activity and has been implicated in the progression and metastasis of several cancers." (PMID 25237831, 2014). "Additionally, studies have shown that RNAi mediated knockdown of EZH2 inhibits the growth and migration of cancer cells and upregulates the tumor suppressor gene BRCA1." (PMID 24587223, 2014). "EZH2 is overexpressed in SEOC, as well as in cancer-associated stromal cells." (PMID 24971229, 2014). "The link between these miRNAs and EZH2 has been demonstrated in numerous experimental settings amongst others investigating the importance of this regulatory mechanism for the onset and progression of various types of cancer including PCa." (PMID 24517338, 2014). "In addition, 3-Deazaneplanocin A (DZNep), an S-adenosyl-L homocysteine hydrolase inhibitor which induces EZH2 protein depletion, leads to cell death in several cancers and tumors." (PMID 24852755, 2014). "Our present data indicating an essential role of Ezh2 specifically for highly proliferating undifferentiated cells would imply that cancer cells might reacquire the similar properties of fetal progenitors." (PMID 25153170, 2014). "Indeed, forced overexpression of Ezh2 leads to cancer phenotypes, and inhibition of EZH2 is a promising cancer therapy." (PMID 25333635, 2014). "Together, these evidences suggest that EZH2 may regulate cancer stem/initiating cell equilibrium in IBC." (PMID 24294976, 2013). "Since DZNep functions as a global potent inhibitors of histone methylation and doesn't act as EZH2 antagonist with high specificity, we further examine that whether these anti-cancer properties exerted by DZNep were attributed to its depletion of EZH2." (PMID 24345883, 2013). "Previous reports have indicated that EZH2 is identified as a downstream mediator of the retinoblastoma protein (pRB) pathway-E2F pathway which controls multiple key cell-cycle regulators during cell proliferation in normal and cancer cells." (PMID 24345883, 2013). "Altogether, our findings unravel a tight and multilayered regulation of DLC1/Rho/ROCK signaling by EZH2, which may underpin a critical epigenetic driven event in promoting cancer metastasis." (PMID 23826380, 2013). "EZH2 appears to be a promising therapeutic target in GBMs because of the extremely high frequency of overexpression and the observations that EZH2 inhibition severely retards the growth of cancer cells." (PMID 24260522, 2013). "In addition, KLF2 is involved in the inhibition of proliferation and migration and is silenced in cancer by the Polycomb repressive complex 2 protein EZH2." (PMID 23565812, 2013). "Given the facts that Ki-67 is a well-established biomarker for cancer cell proliferation and EZH2 has putative proproliferative role during cancer progression, we then ask whether the positive correlation between EZH2 and Ki-67 existed in TSCC." (PMID 24345883, 2013). "Overexpression of EZH2 also leads to the silencing of multiple miRNAs in cancer." (PMID 24348513, 2013). "EZH2 was readily detected and identified in nucleus in cancer cell lines examined." (PMID 24345883, 2013). "Furthermore, accumulated evidence indicates that a myriad of direct or indirect target genes including E-cadherin, INK-ARP(p14,p16) are partially responsible for the essential roles of EZH2 in various cancers." (PMID 24345883, 2013).
cancer (continued). "Since EZH2 has been shown to be regulated by the proteasome in various cancer cells, we asked whether the decrease in EZH2 protein levels might be a result of proteasome degradation during neuron differentiation of hMSCs." (PMID 23526793, 2013). "These analyses led to the novel conclusion that activation of HDAC4 and the histone methylase EZH2 are mutually exclusive and represent two distinct biologic fates in cancer cells, one related to growth factor signaling and the other related to inflammatory signaling." (PMID 24079712, 2013). "Enforced expression of EZH2 increased cancer cell proliferation, epithelial-mesenchymal transition, metastatic spreading and other oncogenic properties, whereas its depletion inhibited cell proliferation, migration and invasion and induced cell apoptosis and senescence both in vitro and in vivo." (PMID 24345883, 2013). "EZH2 overexpression often correlated with advanced stages and poor prognosis in these cancers." (PMID 24345883, 2013). "Gene silencing mediated by EZH2-induced H3K27me3 has been involved in diverse fundamental cellular processes, such as cell fate decision, cell cycle progression, apoptosis and senescence, stem cell maintenance and cancer development." (PMID 24345883, 2013). "Overexpression of EZH2 has been found in a number of human cancers." (PMID 24367611, 2013). "Since E-cadherin has been well established as a master regulator in cancer invasion and metastasis and a key downstream target of EZH2, we then wonder whether E-cadherin induction was responsible for the impaired migration and invasion induced by DZNep." (PMID 24345883, 2013). "More importantly, given the advantages of specific chemical compounds including convenient to use and reversible nature of epigenetic modifications behind carcinogenesis, administration of small molecules targeting EZH2 seems to be a plausible and appealing way as a novel anti-cancer strategy." (PMID 24345883, 2013). "Currently, there are active efforts to develop EZH2 inhibitors for cancer therapy, and our data suggest that they may also be useful to suppress epigenetic plasticity and its physiological consequences, such as metastasis and drug resistance." (PMID 24367927, 2013). "Interestingly, it has been recently shown that, upon interferon alpha treatment, EZH2 inhibits ΔNp73α expression in hepato-cellular carcinoma cells (HCC) by direct binding to the p2 promoter." (PMID 23516355, 2013). "Over-expression of EZH2 has been strongly linked with cancer progression partly because PRC2 inhibits E-cadherin expression, which promotes epithelial-to-mesenchymal transition (EMT) in cancer cells, a phenomenon that is reminiscent of CSCs or CSLCs." (PMID 22442719, 2012). "In addition to the direct regulation of EZH2 activity, cancer therapy that blocks EZH2-mediated oncogenic signalling is warranted." (PMID 22187039, 2012). "Together, these studies indicate that EZH2 has an essential and multi-faceted role in cancer." (PMID 22187039, 2012). "Recently, EZH2 has also been found to regulate signaling pathways associated with cellular metabolism such as the Ras GTPase-activating protein DAB2IP and the adrenergic receptor-beta-2 ADRB2, promoting cancer progression." (PMID 22272343, 2012). "This is particularly interesting given the potential dual role of EZH2 in different cancer types." (PMID 22629454, 2012). "The involvement of EZH2 overexpression in cancer stem cells and cancer progression was consolidated by recent finding, which elucidates that EZH2 contributing not only to cancer stem cell formation but also to expansion of an aggressive cancer stem cell population that promotes cancer progression." (PMID 22187039, 2012). "EZH2 is a transcriptional repressor that catalyzes histone H3K27 trimethylation and its upregulation in cancer is due in part to MEK-ERK-mediated transcriptional activation and/or by loss of miR-101 that negatively regulates EZH2 expression by binding to its 3'-UTR." (PMID 22948084, 2012).
cancer (continued). "In addition, increasing evidences suggest that overexpression of EZH2 in cancers contribute to a more aggressive clinical behavior, which is likely mediated in part through silencing the expression of cell cycle inhibitors p15INK4B and p16INK4A." (PMID 23300840, 2012). "Since excessive cell proliferation is a common feature of PAH and some cancers, it is hypothesized that EZH2 plays a role in the proliferation of pulmonary arterial smooth muscle Cells (PASMCs) in PAH." (PMID 22662197, 2012). "In addition, the strong relationship between EZH2 and proliferation index in carcinoma is reconfirmed." (PMID 23133536, 2012). "In addition, in primary carcinomas, strong expression of both EZH2 and HOTAIR also trends with worse survival." (PMID 23133536, 2012). "Moreover, the recent development of EZH2 inhibitors as anti-cancer therapeutics opens the interesting opportunity of a combined chemotherapy/immunological approach for treating EZH2-expressing LCs." (PMID 22053850, 2011). "EZH2 promotes cancer cell proliferation in vitro and in vivo." (PMID 21297974, 2011). "The importance of epigenetic regulation in cancer is also underscored by the findings that a number of genes encoding critical epigenetic regulators, including MLL1, MEN1, EZH2, SETD2, JARID1C, BAF180 and UTX, have been identified as mutated in various human cancers." (PMID 21544224, 2011). "Of these, KMT1C (G9a) when expressed in NSCLC cells causes an aggressive phenotype promoting both invasion and metastasis by silencing expression of the cell adhesion molecule Ep-CAM, while overexpression of KMT6 (EZH2) has also been linked to both poor prognosis and cancer aggressiveness in NSCLC." (PMID 24212667, 2011). "EZH2 is essential for promoting chemotherapy resistance in cancer cells in vitro and in vivo, and EZH2 could be a potential novel epigenetic target to overcome drug resistance." (PMID 21814622, 2011). "EZH2 is overexpressed in various cancers, which correlates to decreased patient survival." (PMID 21321380, 2010). "Importantly, two recent studies indicated that miR-26a targets Ezh2 and other studies suggested these two miRNAs are downregulated in cancers." (PMID 20478051, 2010). "We had initially speculated that the drug-induced degradation of EZH2 alone could lead to derepression of differentiation-specific genes in embryonic cancer stem cells." (PMID 20502711, 2010). "Taken together, Ezh2 plays an oncogenic role in PCa and elucidating the mechanisms that regulate Ezh2 function may provide fundamental therapeutic insight in treating this cancer." (PMID 20478051, 2010). "Kaplan Meier cancer specific survival curves of the whole cohort of patients and of the non-metastatic subgroup revealed a worse prognosis in patients with more than 25% nuclear EZH2 staining." (PMID 20920340, 2010). "For example, EZH2 mutations have been found to be frequent in large B-cell lymphomas of germinal-cell origin and suggested to underlie the enhanced methylation at PRC2 targets that have been observed in this cancer type." (PMID 20565864, 2010). "EZH2 degradation by these compounds could also be observed in other human cancer cell lines, although to varying degrees." (PMID 20502711, 2010). "Increasing evidence suggests an essential role of Ezh2 in cancers." (PMID 20478051, 2010). "Therapeutically, this information may provide significant values in patient stratification for potential clinical use of EZH2 inhibitors as anti-cancer agents." (PMID 19340297, 2009). "Similarly, knocking down of EZH2, a human homolog of E(z), led to a global decrease in H3K27me3 in cancer cells." (PMID 19270745, 2009). "EZH2 is overexpressed and correlates with poor prognosis in many cancers." (PMID 20028503, 2009). "Importantly, as a newly identified EZH2 target with prognostic value, it has implications in patient stratification for cancer therapeutic targeting EZH2-mediated gene repression." (PMID 19340297, 2009).